BAG3 (BAG cochaperone 3)
Description:
Co-chaperone and adapter protein that connects different classes of molecular chaperones including heat shock proteins 70 (HSP70s), e.g. HSPA1A/HSP70 or HSPA8/HSC70, and small heat shock proteins (sHSPs), e.g. HSPB8. Acts as a nucleotide-exchange factor (NEF) promoting the release of ADP from HSP70s, thereby triggering client protein release. Nucleotide release is mediated via BAG3 binding to the nucleotide-binding domain (NBD) of HSP70s, whereas client release is mediated via binding to the substrate-binding domain (SBD). Has anti-apoptotic activity. Plays a role in the HSF1 nucleocytoplasmic transport.
Synonyms: BAG-3; BIS; CAIR-1; CMD1HH; CMT2JJ; HMND15; MFM6
Tractability: PROTAC: UniProt records ubiquitination sites on it; ubiquitination databases record sites on it; its protein half-life has been measured.
Gene: Protein-coding gene on chromosome 10 (119,650,879 to 119,677,913, forward strand). Ensembl gene ENSG00000151929.
Subcellular location: Nucleus; Cytoplasm
Subcellular location (Human Protein Atlas): Cytosol; Basal body; Nucleoplasm
Pathways (Reactome):
Cellular responses to stimuli: Regulation of HSF1-mediated heat shock response
Gene Ontology:
Molecular function: adenyl-nucleotide exchange factor activity; cadherin binding; protein binding; protein-folding chaperone binding; protein-macromolecule adaptor activity; dynein intermediate chain binding; protein carrier chaperone; protein-containing complex binding
Biological process: cellular response to heat; cellular response to unfolded protein; extrinsic apoptotic signaling pathway via death domain receptors; muscle cell cellular homeostasis; negative regulation of striated muscle cell apoptotic process; positive regulation of aggrephagy; positive regulation of protein export from nucleus; positive regulation of protein import into nucleus; protein folding; protein stabilization; aggresome assembly; negative regulation of apoptotic process; protein transport along microtubule; autophagosome assembly; chaperone-mediated autophagy; extrinsic apoptotic signaling pathway; negative regulation of establishment of protein localization to mitochondrion; spinal cord development
Cellular component: cytoplasm; cytosol; nucleoplasm; nucleus; protein folding chaperone complex; aggresome; membrane; stress fiber; Z disc
Genetic constraint (gnomAD): Loss-of-function variants: 14 observed, 40.71 expected, observed/expected ratio (o/e) 0.34, 90% interval 0.23 to 0.54. The upper end of that interval is the gene's LOEUF score, 0.54, which puts it in group 2 of 6, group 1 being the genes least tolerant of losing a copy. Missense variants: 788 observed, 783.3 expected, observed/expected ratio (o/e) 1.01, 90% interval 0.95 to 1.07. Synonymous variants: 302 observed, 312.63 expected, observed/expected ratio (o/e) 0.97, 90% interval 0.88 to 1.06.
Gene-disease validity (ClinGen):
ClinGen rates the evidence that BAG3 causes each of these diseases.
dilated cardiomyopathy 1HH (autosomal dominant): Definitive. Any familial isolated dilated cardiomyopathy in which the cause of the disease is a mutation in the BAG3 gene.
myofibrillar myopathy (autosomal dominant): Definitive.
Homologues: Orthologues: chimpanzee BAG3 (99% identical), macaque BAG3 (97% identical), guinea pig BAG3 (88% identical), rat Bag3 (86% identical), mouse Bag3 (85% identical), rabbit BAG3 (85% identical), dog BAG3 (76% identical), pig BAG3 (74% identical), tropical clawed frog bag3 (44% identical), zebrafish bag3 (30% identical), Drosophila melanogaster stv (14% identical). Paralogues in human: BAG4 (18% identical), BAG5 (14% identical).
Diseases named in the same sentence as BAG3 in open-access papers:
BAG3 is named in the same sentence as 225 diseases in open-access papers, as found by Europe PMC text mining. Sharing a sentence is not in itself a finding about the gene and the disease. The quoted sentences say what the papers report.
cardiomyopathy (69 papers, 2014 to 2026). A disease of the heart muscle or myocardium proper. "We recently reported that a frameshift mutation in the second exon of the zebrafish bag3 gene resulted in cardiomyopathy‐like phenotypes at 6 months of age, termed bag3e2/e2 cardiomyopathy." (PMID 40922543, 2025). "BAG3 deficiency impairs autophagy and protein quality control, leading to myocyte dysfunction and cardiomyopathy." (PMID 41172738, 2025). "Genetic testing using a custom next-generation sequencing cardiomyopathy gene panel identified a heterozygous frameshift mutation in exon 4 of the BAG3 gene [NM_004281: c.1128del: p.(Ser377AlafsTer47)]." (PMID 40278180, 2025). "BAG3 mutations include missense, truncations, and frame shifts, with the E455-R477 region significantly correlated with cardiomyopathy." (PMID 41250780, 2025). "De novo or autosomal dominant BAG3 gene variants cause a wide range of skeletal and cardiac muscle diseases encompassing Charcot–Marie–Tooth disease, myofibrillar myopathy, cardiomyopathy or a combination of them." (PMID 40493734, 2025). "This cohort study examines associations of common and rare protein-altering variants in TNN and BAG3 with late-onset cancer therapy–related cardiomyopathy risk in adult childhood cancer survivors." (PMID 40540274, 2025). "This provides important insights into the role of BAG3 in cardiomyopathies and the increased risk of arrhythmias in HF." (PMID 40278180, 2025). "What is the association of TTN and BAG3 with late-onset cancer therapy–related cardiomyopathy (CCM) among childhood cancer survivors?" (PMID 40540274, 2025). "For instance, while the association of BAG3 with both cardiomyopathy and Parkinson’s disease (PD) has been reported, the genetic associations are in the opposite directions, i.e., the risk allele in DCM is protective against PD." (PMID 39457090, 2024). "Using a BAG3-associated cardiomyopathy zebrafish model, we demonstrated the feasibility of a F0-based genetic assay that enables rapid discovery of disease modifiers." (PMID 35481478, 2023). "High levels of BAG3 are associated with insensitivity to chemotherapy in malignant cells whereas both loss of function and gain of function variants are associated with cardiomyopathy." (PMID 36980278, 2023). "In this article, we initially identified the modifying effects of dnajb6b gene deficiency on bag3 cardiomyopathy by using classic genetic analysis." (PMID 35481478, 2023). "The first was a girl with cardiomyopathy and sensory axonal neuropathy that underwent cardiac transplantation at 15 years and suffers from rotatory scoliosis due to BAG3 mutation." (PMID 40757566, 2023). "Further studies are, therefore, warranted to elucidate the detailed mechanisms that underlie the modifying effects of myh9b on bag3 cardiomyopathy." (PMID 35481478, 2023). "Mutations in Bcl-2-associated athanogene-3 (BAG-3) can cause a rare subtype of myofibrillar myopathies (MFMs), characterized by progressive muscle weakness, cardiomyopathy, and severe respiratory insufficiency in childhood." (PMID 35029900, 2022). "BAG3 is highly expressed in the skeletal and cardiac muscles, and mutations in the BAG3 gene cause cardiomyopathy." (PMID 34943839, 2021). "Because BAG3 is a key cardiomyopathy gene, with several reported DCM-causing mutations occurring across the gene, many more causative variants in the gene are likely still to be discovered amongst PPCM patients." (PMID 33467574, 2021). "Mutations in BAG3 can cause cardiomyopathy through impairments in any of the protein’s diverse functions." (PMID 33467574, 2021). "BAG3 gene mutations are some of the most documented chaperone-associated mutations in cardiomyopathy." (PMID 33467574, 2021).
cardiomyopathy (continued). "Cardiac-specific loss of Bag3 results in cardiomyopathy in mice, and myofibrillar disruption in human induced pluripotent stem cell derived cardiomyocytes." (PMID 33637999, 2021). "BAG3 targets misfolded proteins for lysosomal degradation via the autophagy pathway and mutations in BAG3 have resulted in proteotoxic stress and severe cardiomyopathy." (PMID 32751309, 2020). "sHsp mutations as well as those in proteostatic machinery components, such as BAG3, have been implicated as mediators of cardiomyopathy." (PMID 32581848, 2020). "The cardiomyopathy mutations and the role of BAG3 in the heart have been recently reviewed by others." (PMID 32093037, 2020). "For example, studies modeling cardiomyopathy-associated mutations in BAG3 in iPSC-derived cardiac myocyte demonstrate myofibrillar disarray and marked proteostatic dysfunction without appearance of protein aggregates." (PMID 32581848, 2020). "BAG3 cardiomyopathy is likely of a loss-of-function nature because truncation mutations in BAG3 are frequently found in DCM patients, and a cardiac-specific Bag3-knockout mouse manifests DCM phenotypes." (PMID 31492659, 2019). "To model BAG3 cardiomyopathy, we targeted the 2nd exon to generate bag3 loss-of-function mutants via transcription activator-like effector nuclease (TALEN) technology." (PMID 31492659, 2019). "In conclusion, our findings suggest that the TNNT2 variant especially in combination with the BAG3 variant is associated with a high propensity to life-threatening cardiomyopathy presenting from childhood and young adulthood." (PMID 28669108, 2017). "Our findings suggest that the variants in TNNT2 and BAG3 are associated with a high propensity to life-threatening cardiomyopathy presenting from childhood and young adulthood." (PMID 28669108, 2017). "BAG3 ablation in mice results in a lethal cardiomyopathy soon after birth and mutations of this gene have been associated with different cardiomyopathies including stress-induced Takotsubo cardiomyopathy (TTC)." (PMID 26512958, 2015). "Variants in BAG3 have definitive evidence for causing cardiomyopathies." (PMID 41054850, 2025). "Finally, by conducting single-nucleus RNA sequencing (snRNA-Seq) of cardiac tissue from BAG3 cardiomyopathy patients, we observed that pathogenic variants in BAG3 driving DCM activate a fibrogenic program in cardiac fibroblasts." (PMID 39744939, 2025). "While BAG3 has been identified as a causative gene for dilated cardiomyopathy, the major pathological events in BAG3‐related cardiomyopathy that could be targeted for therapeutic benefit remain to be discovered." (PMID 40922543, 2025). "Furthermore, BAG3 mutations can cause myofibrillar myopathies and cardiomyopathy, in which accumulation of BAG3 or myofibrillar proteins, e.g., myotilin, desmin, and αB-crystallin, can be found." (PMID 39012547, 2024). "Likewise, abnormal protein handling and degradation plays an important role in cardiomyopathy development due to mutations in genes such as BAG3 and FLNC." (PMID 37887855, 2023). "Here, we unveiled the modifying effects of dnajb6b deficiency on bag3 cardiomyopathy." (PMID 35481478, 2023). "We identified common variants within genes implicated in cardiomyopathies (e.g. BAG3, FHOD3, PLN), suggesting sarcomere homeostasis during mechanical stress may affect diastolic function in both health and disease." (PMID 35479509, 2022). "In addition, several of the most significantly altered genes were those implicated in cardiomyopathy and heart failure, such as BAG3 and FLNC, and many heat-shock proteins, indicating the activation of cardiac stress-response pathways relevant to CFZ-associated cardiotoxicity." (PMID 41683782, 2026). "Interestingly, BAG3 is predominantly expressed in the heart and skeletal muscle cells and mutations in the BAG3 gene are associated with different variants of cardiomyopathies such as hypertrophic cardiomyopathy (HCM) and DCM or protein aggregation diseases such as MFM." (PMID 33137814, 2020).
cardiomyopathy (continued). "Indeed, in instances where BAG3 mutations do induce protein aggregates and provoke cardiomyopathy, the mutant BAG3 protein acquires a gain-of-function aggregate-prone state, which forms protein aggregates with Hsp70, its natural binding partner and Hsp70 clients." (PMID 32581848, 2020). "This overexpression was sufficient to restore defective proteostasis and rescue cardiac dysfunction in the bag3 cardiomyopathy model." (PMID 40922543, 2025). "The GWAS of NT-proBNP levels identified cardiomyopathy- or heart failure-associated genetic loci (eg, HSPB7/CLCNKA, CDKN1A, TTN, FLNC, and BAG3)." (PMID 41054850, 2025). "Together, this study uncovered accelerated cardiac senescence as a key pathological event in bag3 cardiomyopathy and reveals that manipulating the mTOR‐Tfeb‐Fabp7a axis can mitigate this pathology and confer cardioprotective effects." (PMID 40922543, 2025). "Collectively, these data confirm fabp7a as a modifier gene for bag3 cardiomyopathy that can be inhibited to exert cardioprotective effects." (PMID 40922543, 2025). "First, they expand our understanding of DCM pathogenesis and highlight the phenotypic heterogeneity of BAG3-related cardiomyopathy." (PMID 40278180, 2025). "The increase in contractile performance of BAG3-/- iPSC-CMs on dynamic substrates indicated a hypercontractile phenotype of BAG3-/- iPSC-CMs, as an early sign of cardiomyopathy." (PMID 41328308, 2025). "Noteworthy, mutations in BAG3, the obligatory partner of HSPB8, cause cardiomyopathy, besides neuropathy and myopathy, and mutations in other HSPBs (HSPB5, HSPB6, and HSPB7) also associate with cardiac pathology." (PMID 40467930, 2025). "Nevertheless, our genetic studies suggested that fabp7a is a potential therapeutic modifier gene for bag3 cardiomyopathy." (PMID 40922543, 2025). "While the expression of Bag3 protein has been linked to aging, as evidenced by a significantly elevated Bag3/Bag1 ratio in the neurons of aged rodent brain, it remains unclear whether cardiac senescence contributes to the pathogenesis of bag3e2/e2 cardiomyopathy." (PMID 40922543, 2025). "While the inhibition of fabp7a recapitulated the cardioprotective effects of mtor inhibition and tfeb overexpression on the bag3 cardiomyopathy, activation of fabp7a exacerbated these phenotypes." (PMID 40922543, 2025). "Here, we aim to uncover novel pathological events through genetic studies in a zebrafish bag3 cardiomyopathy model." (PMID 40922543, 2025). "To confirm the salutary modifying effect of fabp7a inhibition on bag3 cardiomyopathy, we generated a stable fabp7a mutant that harbors an 8‐nucleotide deletion." (PMID 40922543, 2025). "Consistent with this genetic evidence, we detected elevated fabp7a expression in the bag3 cardiomyopathy model, whereas cardiomyocyte‐specific overexpression of fabp7a induced dysregulated proteostasis, accelerated cardiac senescence, and cardiac dysfunction." (PMID 40922543, 2025). "Downstream of the mTOR‐Tfeb axis, fabp7a emerged as a candidate therapeutic target gene for bag3 cardiomyopathy." (PMID 40922543, 2025). "Notable genes such as titin (TTN), Bcl2-associated athanogene 3 (BAG3), and lamin A/C (LMNA) are implicated in PPCM, revealing a complex genetic landscape similar to other cardiomyopathies." (PMID 39118717, 2024). "For this purpose, we performed a proteomics study using the BioID proximity-dependent biotinylation method to identify proteins that interact with BAG3, particularly those from the gene sets with expression levels correlated with cardiomyopathies." (PMID 39457090, 2024). "In conclusion, this study highlights the observed interactions of BAG3 with key gene sets that are affected in cardiomyopathies, thereby unveiling some of the molecular mechanisms involved with the cardioprotective effects of BAG3." (PMID 39457090, 2024).
cardiomyopathy (continued). "There is an increased prevalence of rare variants (BAG3, LMNA, MYH7, TCAP, TNNT2, and TTN), particularly TTNtv, in adult and pediatric cancer patients with cancer therapy-induced cardiomyopathy." (PMID 39070560, 2024). "This study highlights BAG3 protein interactions, unveiling the key gene sets affected in cardiomyopathies, which help to explain the molecular mechanisms of the cardioprotective effects of BAG3." (PMID 39457090, 2024). "Genetic profiling reveals a complex landscape with key genes like titin (TTN), Bcl2-associated athanogene 3 (BAG3), and lamin A/C (LMNA) implicated in PPCM, suggesting genetic predispositions and shared pathways with other cardiomyopathies." (PMID 39118717, 2024). "Here, we aim to develop a rapid F0-based genetic assay in adult zebrafish using the bag3 gene knockout (bag3e2/e2) cardiomyopathy model as a paradigm." (PMID 35481478, 2023). "Together, these data confirmed a genetic interaction between dnajb6b and bag3 genes in cardiomyopathy." (PMID 35481478, 2023). "Our data suggest that bag3-mediated cardiomyopathy is characterized by high sensitivity to genetic lesions in the mtor-myh9b signaling axis that affects autophagy initiation, a key step of proteostasis." (PMID 35481478, 2023). "Another potential reason is the different functional consequence between the F0dnajb6be6−MJ and stable dnajb6b+/− on bag3 cardiomyopathy." (PMID 35481478, 2023). "First, by utilizing a classic genetic breeding approach, we identified dnajb6b as a deleterious modifier gene for bag3 cardiomyopathy." (PMID 35481478, 2023). "We showed that effective gene knockdown is maintained in F0 adult fish, enabling recapitulation of both salutary modifying effects of the mtor haploinsufficiency and deleterious modifying effects of the dnajb6b gene on bag3 cardiomyopathy." (PMID 35481478, 2023). "For example, patients with identical cardiomyopathy-causing mutations, such as mutations in RBM20, TNNI3 or BAG3, can manifest highly variable disease onset and severity." (PMID 35481478, 2023). "Together, these results demonstrated that the F0-based genetic assay largely recapitulates salutary modifier effects of the mtor haploinsufficiency on bag3 cardiomyopathy." (PMID 35481478, 2023). "Other highly prioritized genes across multiple lines of evidence include Mendelian cardiomyopathy genes (BAG3, ACTN2, ALPK3)." (PMID 36376295, 2022). "Among them, BCL2-associated athanogene 3 (BAG3) gene mutation is thought to induce a rare MFM subtype VI with clinical features of rapidly progressive limb and axial muscle weakness, cardiomyopathy, and respiratory insufficiency in childhood." (PMID 35029900, 2022). "The set of genes identified by the eQTL and sQTL TWAS was enriched for Mendelian cardiomyopathy genes (BAG3, ACTN2) (hypergeometric p = 0.049)." (PMID 36376295, 2022). "It has been suggested that the subtype of cardiomyopathy is determined by the variant type and site location as seen for other cardiomyopathy-associated genes (e.g., DES, LDB3, BAG3, FHL1)." (PMID 33802723, 2021). "These mice suffer from cardiomyopathy, but with normal BAG3 expression in skeletal muscle survives until around 10 months." (PMID 32093037, 2020). "Analogously, we have demonstrated that TFEB-induced upregulation of HspB8, a BAG3 partner, was essential for chaperoning desmin back to its physiologic localization state in a mouse model of R120G αB-crystallin induced cardiomyopathy." (PMID 32581848, 2020). "Conversely, aberrant BAG3 function/expression has pathophysiological relevance correlated to cardiomyopathies, neurodegeneration, and cancer." (PMID 32121220, 2020).